CXCR4 (C-X-C motif chemokine receptor 4)
Diseases named in the same sentence as CXCR4 in open-access papers (continued):
Sharing a sentence is not in itself a finding about the gene and the disease.
cancer (continued). "It has been verified that many natural products can produce anti-cancer and anti-viral effects through the CXCL12/CXCR4 axis, including flavonoids, isoflavones, bioketones, and isoprenoidyl flavonoids." (PMID 35893797, 2022). "CXCR4 and CXCL12 are both overexpressed in several diseases, including inflammatory disorders and cancer." (PMID 36499357, 2022). "Under the hypoxic conditions prevalent in cancer, hypoxia-inducible factor (HIF)-1α selectively enhances CXCR4 expression and chemotactic responses to CXCL12—including EOC cells, TAMs, and endothelial cells—thus inducing angiogenesis." (PMID 35269786, 2022). "Neoplastic CXCR4 and CXCL12 discriminated PDACs for recurrence-free survival (RFS), while CXCL12 and CXCR7 discriminated patients for cancer-specific survival (CSS)." (PMID 36359736, 2022). "Since then, several nanobodies have been under clinical trials for cancer treatment: anti-HER2 5F7 nanobody, ALX-0141 (target nuclear factor kappa B ligand), DR5Nb1 (target DR5), and ALX-0651 (target CXCR4)." (PMID 35454775, 2022). "Another promising target is CXCR4, the receptor for SDF-1/CXCL12, which is expressed in CAFs, MDSCs and cancer cells." (PMID 36436127, 2022). "Among the EOC tissues examined, CXCR4 expression correlated strongly with expression of proteins related to the epithelial-mesenchymal transition (EMT) and cancer stem cell (CSC), including vimentin, N-cadherin, E-cadherin, CD44, CD133, and NANOG." (PMID 35681259, 2022). "Cancers expressing CXCR4 metastasize to tissues with high levels of CXCL12, such as bone marrow, lymph nodes, lungs, and brain, suggesting that cancer cells utilize the CXCR4/CXCL12 axis to establish metastases." (PMID 35336029, 2022). "This review provides an overview of studies involving CXCR4 and CXCR7 in CRC with an update on their targeting in anti-cancer therapies." (PMID 35406582, 2022). "On the other hand, CXCR4 expression and TGF-β-driven Rho-ROCK-myosin II aid cancer cell-endothelial adhesion." (PMID 36699013, 2022). "The interactions between CXCL12 and CXCR4 or CXCR7 comprise a biological axis that affects the growth, angiogenesis, and metastasis of cancers." (PMID 35079936, 2022). "The analysis indicated that CXCR4, DLC1, and MAP1LC3C were significantly (FDR < 0.25, NP < 0.05) enriched in pathways related to immune response and cancer." (PMID 36173625, 2022). "The chemokine receptor 4 (CXCR4) and its natural ligand CXCL12 play vital roles in the development of cancer, including cell survival, proliferation, and migration." (PMID 35336029, 2022). "Recent evidence verified that CXCL14 binds to CXCR4 and shows a synergistic effect with CXCL12 in cancers." (PMID 35452413, 2022). "CXCL12 acts via CXCR4 and ACKR3 receptors, which are significantly expressed on the cancer cell surface." (PMID 35743888, 2022). "It was worth noting that the expression levels of CXCR4, PPP3R1, HSP90AB1, CXCL10, and S100A12 were substantially elevated in multiple types of cancer tissues." (PMID 36569892, 2022). "Our previously published work in OPMD that dealt with cancer stem cells and markers of chemokine pathways indicated that the presence of CXCL12 (SDF-1) and CXCR4 in oral premalignant and malignant sections correlated with disease progression." (PMID 36009387, 2022). "Chemokine receptor CXCR4 and the atypical chemokine receptor ACKR3 (formerly CXCR7) regulate essential processes in normal physiology and numerous diseases, including cancer, atherosclerosis, neurodegeneration, and autoimmunity." (PMID 35681470, 2022). "miR-1 targets several cancer-related molecules, such as Slug, PI3KCA, FoxP1, Pim-1, HDAC4, CCDN2, and CXCR4, indicating that miR-1-3p regulates the expression of several oncogenic pathways." (PMID 35804872, 2022). "CXCR4 and CXCR5 have been recognized as essential players in cancer biology, with the CXCL12/CXCR4 axis playing a pivotal role in inducing metastases." (PMID 35456016, 2022).
cancer (continued). "Chemokine receptors are expressed by different cancer cells and up-regulation of chemokine-receptor pairs (e.g. (Stromal cell-derived factor 1 (SDF-1/CXCL12)/C-X-C chemokine-receptor type 4 (CXCR4)) promotes metastasis." (PMID 35015084, 2022). "Due to the enhanced cellular uptake mediated by T22 targeting CXCR4 and HA targeting CD44 in malignant cells, our delivery vector can target cancer cells as well as CTCs in whole blood to realize efficient genome editing and mRNA detection." (PMID 35595716, 2022). "M2 macrophages (C6-Mye) were predicted to secrete the factors CXCL12 and CCL4 to attract CD8+ Tex cells by binding to CXCR3/CXCR4 and CCR5 on CD8+ Tex cells, which are known to recruit immunocytes into cancer tissues." (PMID 35562760, 2022). "Our study indicated that VM networks consisting of cancer and CAFs increase N2 neutrophil polarization, which expresses high levels of arginase, CCL2, CXCR4 and MMP-9." (PMID 34485133, 2021). "The expression rate of almost 40% for CXCR4 on HuH6 cells also questioned its role as a CSC marker, even though its role in stemness and drug resistance, as well as metastasis in other cancers, was reported." (PMID 34685577, 2021). "Another CXCR4 antagonist, LY2510924, is also able of suppressing cancer growth and metastasis in multiple preclinical models." (PMID 33463063, 2021). "Lidocaine inhibited cancer progression and metastasis via blocking the signaling of chemokine CXCL12 and the activation of its receptor CXCR4." (PMID 34249706, 2021). "C-X-C chemokine receptor 4 (CXCR4) and its ligand stroma-derived factor 1 (SDF1) are upregulated in various cancers, and CXCR4 inhibition prevents metastasis formation." (PMID 33466236, 2021). "In the last years, intense research was performed to identify and develop CXCR4 antagonists for therapeutic applications in HIV/AIDS, cancer, and inflammatory disorders." (PMID 34552197, 2021). "ACKR3, along with CXCR4, with which it shares a ligand, CXCL12, plays an important role in cancer progression." (PMID 33799570, 2021). "Via blocking the combination of SDF-1 and its receptor CXCR4, AMD3100 (a CXCR4 inhibitor) is able to rapidly promote the accumulation of T cells and effectively eliminate cancer cells by synergizing with an anti-PD-L1 antibody." (PMID 34635121, 2021). "Although CXCR4 antagonists have already been tested in clinical trials in other type of cancers, demonstrating that blocking CXCL12 binding to CXCR4 can interfere with cancer progression, specific blockers of CXCL12 production are still lacking." (PMID 34834449, 2021). "CXCR-4, one of the chemokine receptors belonging to the CXC receptor family, plays a significant role in cancer cell proliferation and migration." (PMID 33854604, 2021). "Elevated expression of C-X-C motif chemokine receptor 4 (CXCR4) correlates with chemotaxis, invasion, and cancer stem cell (CSC) properties within several solid-tumor malignancies." (PMID 34070538, 2021). "Numerous studies using cancer and primary cells have shown that CXCR7 is a functional receptor in various cell types, although each contribution of CXCR7 or CXCR4 to CXCL12-mediated cell migration is still controversial." (PMID 34527817, 2021). "CXCR4 upregulates Survivin via PI3K pathways, which in turn mitigates radiation induced apoptosis in cancer cells." (PMID 34685742, 2021). "The expression of CXCR-4 has been increased upon activation of PKC-ζ in hematopoietic progenitor and cancer cells." (PMID 34885003, 2021). "Although some compounds have been reported to prevent IA, such as the CXCR4 antagonist AMD3100, which targets SDF1/CXCR4 signaling, evidence on the efficacy of strategies to act on IA and their value in cancer therapy are far from conclusive." (PMID 33921099, 2021). "First, we identified which cancer cell lines adequately express CXCR4 and ultimately selected A549 and SPCA-1, which were then transfected with CXCR4 siRNA." (PMID 33637678, 2021).
cancer (continued). "The identified real hub gene CXCL12 (stromal cell-derived factor 1) is an extracellular chemokine, which binds to CXCR4, a G-protein coupled receptor (GPCR) and have been well-recognized as a factor involved in the cancer metastasis." (PMID 34473751, 2021). "Recent advances in the development of radiotracers for various chemokine receptors, particularly of CXCR4, CCR2, and CCR5, shed new light on chemokine-related cancer and cardiovascular research and the subsequent drug development." (PMID 34500609, 2021). "CXCR4+ CSC populations have also been described in other tumors like breast, gastric, renal, and colorectal cancers." (PMID 33530455, 2021). "This anti-cancer effect seems to be mediated by the activity of the ligand-activated PPARγ complex, as a novel PPAR responsive element has been predicted on the CXCR4 promoter." (PMID 34834449, 2021). "In sharp contrast, in recurrent cancer biopsies, there was a significant correlation with the expression of CD66b, IL-17, MPO, and CXCR4." (PMID 34830938, 2021). "Compared with monolayer-culture GBM cell lines, cancer stem cell (CSC) markers such as SOX2, PROM1, POU5F1, MSI1, FUT4, and CXCR4 were upregulated in the spheroids." (PMID 34638384, 2021). "Targeted therapies have been developed to inhibit the CXCR4/SDF-1 axis, and have been evaluated in various cancers." (PMID 33507926, 2021). "FAK is among the intracellular pathways that have shown promise as a target in cancer treatment, in addition to other well-known signaling molecules including RAS-RAF-MEK1/2-ERK1/2, CCR2/CCR5, and CXCR4." (PMID 34771675, 2021). "CXCR4 belongs to G protein-coupled receptor superfamily, which selectively binds to stromal cell-derived factor 1 (SDF-1, also called CXCL12) to promote cancer metastasis." (PMID 33897875, 2021). "Among receptors of CXCL12, CXCR4 can specifically bind to CXCL12 and the role of CXCL12/CXCR4 axis is most broadly explored in cancers." (PMID 33747959, 2021). "The selective CXCR4 antagonist AMD3100 (Plerixafor), has been proven to enhance PBSC collection in cancer patients and is established for this purpose, especially in case of mobilization issues." (PMID 34681247, 2021). "Among these genes, we selected Snai2, also named Slug, as a possible effector molecule of CXCR4/STAT3 signaling, since several reports have shown the role of Slug in IR resistance of various cancer cells." (PMID 33414415, 2021). "The chemokine receptor 4 (CXCR4) and 7 (CXCR7) are G-protein-coupled receptors (GPCRs) activated through their shared ligand CXCL12 in multiple human cancers." (PMID 33937018, 2021). "Among them, CXCR4, which is known as the stromal cell-derived factor-1 (SDF-1) receptor, has been characterized by different cancer types." (PMID 34456716, 2021). "Interaction between CXCL12/CXCR4 initiates the phosphorylation of CXCR4, which supports the calcium flux and activation of PI3K, MAPK signalling and thus induce cancer cell proliferation." (PMID 34975909, 2021). "CXCR4 also stimulates many pathways such as PI3K/Akt, JAK/Stat, Wnt, TGF-β, SMAD, NF-κB, among others, in a variety of cancers, all of which play significant roles in CSC maintenance." (PMID 34685742, 2021). "Consequently, in vivo, the CXCR4 peptide antagonist TN14003 displaces CXCR4+ cancer cells from their niche, rendering them sensitive to apoptotic induction, an observation that could be replicated in vitro when cancer cells are co-cultured with SDF1α-expressing stromal cells." (PMID 34208189, 2021). "Most importantly, both CXCR4 and CCR7 have been proposed to be potential therapeutic targets in cancer treatments." (PMID 34685420, 2021). "In the PDAC model, inhibition of CAF-mediated CXCL12/CXCR4 axis with the CXCR4 inhibitor AMD3100 promoted T-cell accumulation and cancer regression." (PMID 33859752, 2021). "Chemokine receptor signaling was of interest, and we found CXCR4 and CXCR5 comentioned with GPRC5C in a review of vascular development dysregulation relevant to cancer." (PMID 34007962, 2021).
cancer (continued). "The secretion and production of chemokines such as CCL2, CXCR1/2, CXCL12, CXCR4, and CXCL8 play critical roles in cancer development and subsequent metastasis." (PMID 34530822, 2021). "In both cancer entities, AKT further promotes the expression of CXCR4 via stabilization of the transcription factor HIF-1α." (PMID 34064589, 2021). "Experimental performed in mouse models strongly suggest that EPI-X4 blocks CXCR4/CXCL12 cell signaling, thus suppressing the migration and invasion of cancer cells." (PMID 34208189, 2021). "CXCR4 has been studied intensively; it binds stromal cell-derived factor 12 (CXCL12), CD4 and CD74, it is overexpressed in 23 human cancers and plays important roles in immune response, hematopoiesis and pro-tumorigenicity." (PMID 34071917, 2021). "CXCL12 acts as a ligand for chemokine receptor CXCR4 and CXCR712,14,29, and these signaling axes have shown to be hyper activated in cancer with poor clinical outcome." (PMID 33966046, 2021). "Meanwhile, several CXCR4 small‐molecule antagonists—such as BKT140, PRX177561, and POL5551—are also capable of inhibiting cancer growth and metastasis." (PMID 33463063, 2021). "As a pharmacological compound, EPI-X4 behaves like a typical CXCR4 antagonist and blocks CXCL12 mediated signaling and cancer cell migration in vitro and mobilizes stem cells in vivo." (PMID 33941197, 2021). "SDF-1/CXCR-4 signaling exerts its function through activating intermediate molecules like NFĸB, AKT, MMPs, ERK and MAPK in cancer tissues." (PMID 34885003, 2021). "Recently, the endogenous human peptide EPI-X4 was identified as a natural CXCR4 antagonist that effectively blocks CXCL12-mediated receptor internalization and suppresses the migration and invasion of cancer cells towards a CXCL12 gradient." (PMID 33669329, 2021). "Until very recently, CXCR4 was thought to be the only receptor to bind CXCL12; however, CXCR7 has emerged as another receptor for CXCL12, with implications in cancer development." (PMID 33530455, 2021). "CXCR4 is the receptor for CXCL12, and an inhibitor of CXCR4, AMD3100, induces T-cell accumulation and works with PD-L1 blockade to reduce cancer cells in KPC mice." (PMID 34336821, 2021). "AGTR1 can also promote lymph node metastasis by chemokine CXCR4/SDF-1α increases, presenting a cancer-promoting effect." (PMID 34568039, 2021). "When compared with those in low-grade PCa tissues with Gleason scores of 6 (control), the ALDH, CD44, CXCR4 and CD24 protein levels were generally elevated in para-carcinoma tissues." (PMID 34247196, 2021). "IHC detection also showed an increased CXCR-4 and CXCR-7 protein expression in carcinoma tissues of OSCCLN(+) patients compared to that of OSCCLN(-) patients." (PMID 33854604, 2021). "Results show that both CXCR-4 and CXCR-7 mRNA expression in the carcinoma tissue of OSCCLN(+) patients were significantly higher than that in OSCCLN(-) patients." (PMID 33854604, 2021). "Several chemokines and their receptors are overexpressed in cancer and strictly related to cancer progression and metastases such as CCR7, CXCR4 and CXCR7." (PMID 32283655, 2020). "A particularly important role in chemotaxis is played by the chemokine receptor, CXCR4, and by its ligand, CXCL12 (also known as SDF1, stromal cell-derived factor, which initiate directed cell migration in various kinds of cancer." (PMID 32292657, 2020). "CXCL12 binds to CXCR4 and CXCR7 to promote cancer progression and promotes chemoresistance invasion and migration by activating a number of intracellular signaling molecules, including Akt, EGFR, mTOR, NF-κB, and Src." (PMID 32963527, 2020). "Our results suggest that matrine can block the cancer metastasis through the negative regulation of CXCR4 and MMP-9/2 and consequently it can be considered as a potential candidate for cancer therapy." (PMID 32630806, 2020). "Similar to CXCR4, the expression of CXCR7 would give cancer cells a metastasis advantage, by moving cells toward an SDF-1α gradient." (PMID 33292475, 2020).
cancer (continued). "Here, we report the discovery of the geometry of the complex between full-length CXCR4, a prototypical CXC receptor and driver of cancer metastasis, and its endogenous ligand CXCL12." (PMID 32271748, 2020). "Multiple small molecules targeting CXCR4/CXCR7 have been developed and used for preclinical and clinical cancer treatment." (PMID 33363463, 2020). "Preclinical and clinical observations of high CXCR4 and CXCL12 expression levels in different tissues affected by cancer cell invasion highlight their importance as potential targets for delivery strategies with advanced therapies." (PMID 33233846, 2020). "One of CSC markers which involved in hematopoietic stem cell (HSC) mobilization and homing and other cancers metastasis is the chemokine SDF1/CXCL12 and its receptor CXCR4." (PMID 31983166, 2020). "It has been recently found that CXCR4 modulates PI3K/Akt/NF-κB signaling pathway and that both NF-κB and CXCR4 belong to a regulatory network driving the migration of cancer stem cells." (PMID 32432042, 2020). "Although the first known activity of CXCR4 was the regulation of HIV- infection and cancer metastasis, CXCR4 is also an abundantly expressed chemokine receptor throughout embryogenesis." (PMID 33415110, 2020). "MiR-518 also plays a role in the growth and metastasis of several cancers, where it has been identified as a downstream target of the SDF-1/CXCR4 system." (PMID 32692745, 2020). "Although initial studies were centered on the participation of CXCR4 in HIV infection of T cells, its connection to cancer became a hot research topic." (PMID 32232002, 2020). "At the molecular level, CXCR-4 and CXCR-7 have been identified as key promoters of cancer adhesion and migration." (PMID 32554853, 2020). "Cancer-specific promoters such as telomerase reverse transcriptase (TERT), survivin, and chemokine receptor 4 (CXCR4) have enhanced activity in a variety of human and murine cancers, however, little has been published regarding these promoters in dogs." (PMID 33166332, 2020). "Another pathway that is still under investigation in this regard is the already cited SDF-1/CXCR4 pathway, which might partake in this process as well, although there is currently no consensus on the matter, and results seem to be pointing at different directions in different cancers." (PMID 32527062, 2020). "In our study, we focused on actions of matrine upon CXCR4 and MMPs activities in different cancer cell lines A549, DU145, and MIA PaCa-2, which display high basal expression of CXCR4 and MMPs." (PMID 32630806, 2020). "Given that chemokines and their receptors are involved in several aspects of cancer biology, CCR4 blockade with monoclonal antibody (mogamulizumab) and inhibitor of chemokine receptor CXCR4 (AMD3100) are being tested in clinical studies." (PMID 32422889, 2020). "Our research group reported that, upon CXCR4 activation, Akt and ERK show an oscillatory pattern of phosphorylation, similarly to that observed in other cancer cells." (PMID 32784743, 2020). "Thus, the characterization of the CXCR4 genomic landscape may represent a key and promising element in the identification of relevant biomarkers for prognosis, clinicopathological classification, and precision therapy in cancer." (PMID 32260318, 2020). "CXCR4 is crucial for haematopoietic stem cells (HSC) homing, but also cancer cells can exploit this pathway in order to exit the bloodstream and interact with the bone marrow stromal components." (PMID 32527062, 2020). "The only licensed CXCR4 antagonist to date is AMD3100 (Plerixafor), which is used as single injection to mobilize hematopoietic stem cells in cancer patients." (PMID 32994431, 2020). "The C-X-C motif chemokine receptor 4 (CXCR4) is a seven-transmembrane G protein-coupled receptor that is overexpressed in numerous diseases, particularly in various cancers and is a powerful chemokine, attracting cells to the bone marrow niche." (PMID 32867358, 2020).